SNHG1 (small nucleolar RNA host gene 1)
Synonyms: UHG; NCRNA00057; LINC00057; lncRNA16; U22HG
Gene: Long non-coding RNA gene on chromosome 11 (62,851,833 to 62,856,444, reverse strand). Ensembl gene ENSG00000255717.
Gene Ontology:
Biological process: RNA processing
Cellular component: nucleolus
Diseases named in the same sentence as SNHG1 in open-access papers:
SNHG1 is named in the same sentence as 99 diseases in open-access papers, as found by Europe PMC text mining. Sharing a sentence is not in itself a finding about the gene and the disease. The quoted sentences say what the papers report.
breast cancer (37 papers, 2016 to 2026). A primary or metastatic malignant neoplasm involving the breast. "LncRNA Small Nucleolar Host Gene 1 (SNHG1) promoted M2 polarisation in breast cancer-associated macrophages as evidenced by the attenuation of the macrophage RAW 264.7 activation and downregulation of M2 markers after IL4/13 stimulation in SNHG1 knockout conditions." (PMID 40176927, 2024). "Taken together, upregulated SNHG1 is potentially associated with tumorigenesis in breast cancer." (PMID 34806925, 2021). "High SNHG1 levels were closely linked to reduced survival rates in breast cancer patients." (PMID 34806925, 2021). "Recent studies have shown that the exosomal SNHG1 secreted by hypoxic breast cancer induces angiogenesis and promotes tumor growth and metastasis." (PMID 41507135, 2026). "Beyond breast cancer, SNHG1 has also been described as an oncogene in several other cancers, including colorectal, prostate, and bladder cancer." (PMID 41283331, 2025). "Experimental silencing of SNHG1 reduced the proliferative, migratory, and invasive activity of breast cancer cells." (PMID 41283331, 2025). "These interactions reveal the complex mechanisms of miR-193a-5p in cancer development.miR-193a-5p inhibits breast cancer progression by targeting SNHG1 and inactivating the oncogene HOXA1." (PMID 40161373, 2025). "Exosomal SNHG1 from hypoxic breast cancer cells can promote tumor angiogenesis and growth by regulating the miR-216b-5p/JAK2 axis." (PMID 40486870, 2025). "Recent studies have shown that SNHG1 promotes immune evasion in breast cancer cells by regulating miRNA, while SNHG6 facilitates colorectal cancer and glioma progression by modulating miR-101-3p expression." (PMID 39530098, 2024). "Another study uncovered that SNHG1 silencing contributed to decline of tumor growth of breast cancer in vivo." (PMID 36230661, 2022). "Suppression of STAT6 phosphorylation by knockdown of lncRNA small nucleolar RNA host gene 1 (SNHG1) inhibited M2 macrophage polarization in breast cancer." (PMID 36153596, 2022). "Studies have reported that lncRNA Snhg1 can regulate the differentiation of Treg cells and can affect the immune escape of breast cancer cells by regulating the miR-448/IDO axis." (PMID 35719364, 2022). "The lncRNA small nucleolar RNA host gene 1 (SNHG1) can affect the immune escape of breast cancer by regulating the differentiation of Treg cells." (PMID 36032137, 2022). "In breast cancer (BC), exosomal SNHG1 promotes the proliferation, migration, and angiogenesis of HUVECs via the miR-216b-5p/JAK2 axis." (PMID 35326397, 2022). "SNHG1 was found to be significantly upregulated in human breast cancer tissues and cell lines and shown to promote breast cancer cell proliferation and metastasis both in vitro and in vivo." (PMID 36139687, 2022). "SNHG1 silencing has been shown to inhibit the proliferative, migratory, and invasive activity of breast cancer cells." (PMID 34806925, 2021). "The culmination of these data suggests that SNHG1 represents a potential therapeutic target for breast cancer chemotherapy." (PMID 34806925, 2021). "Our findings demonstrated that SNHG1 is significantly upregulated in breast cancer tissues and cells." (PMID 34806925, 2021). "Firstly, Chipbase database analysis exhibited a close association between SNHG1 and EZH2 levels in breast cancer tissues." (PMID 34806925, 2021). "Our data revealed that SNHG1 was upregulated in breast cancer, and silencing SNHG1 suppressed tumor progression and cisplatin resistance of breast cancer cells." (PMID 34806925, 2021). "Prominently, SNHG1 silencing suppressed tumor progression and sensitized breast cancer cells to DDP via epigenetically silencing miR-381." (PMID 34806925, 2021). "In summary, SNHG1 silencing suppressed tumor progression and overcame breast cancer cell DDP resistance via the epigenetic suppression of miR-381 expression." (PMID 34806925, 2021).
breast cancer (continued). "SNHG1 was reported to function as a cancer driver in a range of important human malignancies, including breast cancer." (PMID 34806925, 2021). "The mechanisms through which SNHG1 upregulation contributes to breast cancer progression and DDP resistance remains indescribable." (PMID 34806925, 2021). "Taken together, we indicated the essential role of lncRNA SNHG1 in macrophage polarization and the interaction with breast cancer cells." (PMID 34618681, 2021). "Collectively, we demonstrated the important role of lncRNA SNHG1 in macrophages and breast cancer cells interaction." (PMID 34618681, 2021). "Our study revealed that SNHG1 served as a novel therapeutic target for breast cancer chemoresistance." (PMID 34806925, 2021). "To further explore the role of SNHG1 in breast cancer development, we examined SNHG1 expression in tumor and adjacent normal tissues through qRT-PCR analysis." (PMID 34806925, 2021). "In the present study, we found that SNHG1 expression was significantly upregulated in breast cancer tissues and cells." (PMID 32497022, 2020). "We also explored the effect of SNHG1 on breast cancer cell proliferation in vivo using a xenograft mouse model." (PMID 32497022, 2020). "Here, we found that SNHG1 expression was significantly upregulated in human breast cancer tissues and cell lines." (PMID 32497022, 2020). "Together, these data suggest that SNHG1 plays a role in breast cancer cell migration, invasion, survival, and proliferation." (PMID 32497022, 2020). "To explore the function of SNHG1 in breast cancer progression, we first examined the expression of SNHG1 in 86 paired breast cancer tissues and adjacent normal tissue using Q-RT-PCR assay." (PMID 32497022, 2020). "Since SNHG1 was most highly expressed in MDA-MB-231 cells, we chose MDA-MB-231 cells to study the function of SNHG1 in breast cancer progression." (PMID 32497022, 2020). "In breast cancer, small nucleolar RNA host gene 1 (SNHG1) negatively regulates the protein level of IDO to inhibit Treg cells differentiation and impede immune escape." (PMID 33194608, 2020). "We explored the function of SNHG1 in breast cancer cells using in vitro and in vivo experiments and found that SNHG1 promotes breast cancer metastasis and proliferation." (PMID 32497022, 2020). "Although there has been a preliminary report of the function of SNHG1 in breast cancer, our study reveals a novel competing endogenous RNA (ceRNA) axis to elucidate the role of SNHG1 in breast cancer progression." (PMID 32497022, 2020). "Collectively, our study demonstrates that SNHG1 promotes breast cancer cell proliferation and metastasis by acting as a sponge of miR-193a-5p to activate HOXA1 expression." (PMID 32497022, 2020). "The result suggested SNHG1 expression was upregulated in 54 out of 86 breast cancer clinical samples." (PMID 32497022, 2020). "Next, we examined the effect of SNHG1 downregulation on breast cancer cell migration and invasion by transwell assays." (PMID 32497022, 2020). "Notably, SNHG1 has been identified as a significant regulator that facilitates tumorigenesis, and its expression levels are markedly elevated in breast cancer cells." (PMID 40303981, 2025). "In addition to miRNAs, lncRNA SNHG1 acts as a tumor promoter in various cancers, including colorectal cancer, breast cancer, and prostate cancer." (PMID 40486870, 2025). "Moreover, SNHG1 has been detected in exosomes; exosomes derived from hypoxic breast cancer cells were shown to promote proliferation, migration, and angiogenesis in human umbilical vein endothelial cells (HUVECs)." (PMID 41283331, 2025). "Exosomal Small Nucleolar RNA Host Gene 1 (SNHG1) from hypoxic breast cancer cells could enhance tumour angiogenesis and growth by regulating the miR-216b-5p/JAK2 axis." (PMID 38794316, 2024).
breast cancer (continued). "Small nucleolar RNA host gene 1 (SNHG1), a long noncoding RNA (lncRNA) spanning approximately 1.6 kb and located at chromosome 11q12.3, has been found to be abnormally overexpressed in various cancers, including pituitary and breast cancers." (PMID 38365726, 2024). "SNHG1 silencing exerts the tumor-suppressive effect in breast cancer." (PMID 35836822, 2022). "Likewise, SNHG1 participates in immune escape by regulating T cells in renal cell carcinoma and breast cancer." (PMID 35646635, 2022). "SNHG1 actions as an oncogenic role in breast cancer through regulating LMO4 expression." (PMID 35836822, 2022). "Together with the findings of the previous studies, we suspected that SNHG1 may epigenetically suppress miR-381 expression via recruiting EZH2 in breast cancer cells." (PMID 34806925, 2021). "Herein, we explored the mechanisms through which SNHG1 modulates breast cancer tumor progression." (PMID 34806925, 2021). "In our study, we predicted that the lncRNA SNHG1 may play a key role in breast cancer by epigenetically silencing miR-381." (PMID 34806925, 2021). "SNHG1 promotes invasion and proliferation of breast cancer by targeting miR-382." (PMID 34122108, 2021). "Recently, SNHG1 was revealed to be upregulated and promoted tumor progression in breast cancer." (PMID 34806925, 2021). "A recent study demonstrated that forced LMO4 expression could counteract breast cancer cell cycle redistribution and inhibit cell migration in vitro alongside tumor growth inhibition in vivo induced by siRNA-mediated lncRNA SNHG1 knockdown." (PMID 34447693, 2021). "Moreover, SNHG1 was significantly upregulated in breast cancer cells, and correlated with shorter overall survival in breast patients (P = 0.0137)." (PMID 34806925, 2021). "Herein, we show that SNHG1 was high-expressed in breast cancer tissues/cells, the silencing of which could prevent the metastatic and DDP-resistant phenotypes of breast cancer cells." (PMID 34806925, 2021). "In breast cancer, many lncRNAs such as MIAT (myocardial infarction-associated transcript), SNHG1 (small nucleolar RNA host gene 1), and MALAT1 (metastasis-associated lung adenocarcinoma transcript 1) have been reported to participate in the occurrence, progression, and metastasis of tumors 27-29." (PMID 31892853, 2020). "Next, we explored the function of SNHG1 in breast cancer cell proliferation." (PMID 32497022, 2020). "Furthermore, HOXA1 overexpression can eliminate the effect of SNHG1 silencing in breast cancer cells." (PMID 32497022, 2020). "Next, we examined the effect of SNHG1 on breast cancer cell metastasis in an in vivo mouse model." (PMID 32497022, 2020). "Recent reports have suggested that SNHG1 is aberrantly expressed and contributes to tumorigenesis in several types of human malignances, such as glioma, lung carcinoma, cholangiocarcinoma, breast cancer, hepatocarcinoma 17 and prostate cancer." (PMID 32885590, 2020). "To confirm that HOXA1 is involved in the SNHG1 pathway in breast cancer progression, we tested whether enforced HOXA1 expression would eliminate the effect of SNHG1 silencing in MDA-MB-231 cells." (PMID 32497022, 2020). "For example, it was found that SNHG1 expression was increased in breast cancer." (PMID 33009370, 2020). "Silencing of SNHG1 in breast cancer cells inhibited cell proliferation, migration, and invasion and, thus, SNHG1 may play an important role in breast cancer development." (PMID 32497022, 2020). "As expected, SNHG1 expression was higher in the breast cancer cell lines than in the MCF10A cells." (PMID 32497022, 2020). "In addition, a recent study reported that SNHG1 promoted breast cancer cell growth and invasion by regulating miR-382." (PMID 32497022, 2020). "Here, we found that SNHG1 could directly interact with miR-193a-5p and regulate its expression in breast cancer cells." (PMID 32497022, 2020).
breast cancer (continued). "Our findings indicate that the SNHG1 lncRNA may become a potential biomarker and clinical target in breast cancer treatment." (PMID 32497022, 2020). "The findings suggest that SNHG1 may serve as a potential therapeutic target for breast cancer." (PMID 38794316, 2024). "For Example, in breast cancer, overexpression of lncRNA small nucleolar RNA host gene 1 (SNHG1) could decrease immune escape and tumor progression by enhancing the expression of miRNA- 448 and repression of Indoleamine 2,3-dioxygenase (IDO) level, resulting in inhibition of Treg differentiation." (PMID 36207500, 2022). "Therefore, the aim of our study was to reveal the function and epigenetic mechanism of lncRNA SNHG1 in breast cancer, which may provide for novel insights into therapeutic targets and functional mechanism for breast cancer." (PMID 34806925, 2021). "Specifically, in breast cancer (BC) models, upregulation of lnc-SNHG1 in CD4+ TILs promotes their differentiation into Tregs by interacting with miR-448, a negative regulator of indoleamine 2,3-dioxygenase (IDO)." (PMID 34943820, 2021). "Moreover, miR-381 could be epigenetically suppressed by SNHG1 and miR-381 inhibition could partly reverse the effect of SNHG1 knockdown on breast cancer cells." (PMID 34806925, 2021). "Thus, SNHG1 can function as an oncogenic gene in breast cancer and SNHG1 silencing may be effective for breast cancer chemotherapy." (PMID 34806925, 2021). "Therefore, we aimed to investigate the functional role of SNHG1/miR-381 axis in breast cancer." (PMID 34806925, 2021). "Hence, we further investigated whether SNHG1 was an epigenetic suppressor of miR-381 via recruiting EZH2 in breast cancer cells." (PMID 34806925, 2021). "However, whether SNHG1 affects breast cancer chemoresistance remains uncertain, making this a key topic worthy of further experimental evaluation." (PMID 34806925, 2021). "Moreover, SNHG1 and miR-193a-5p expression levels in breast cancer tissues negatively correlated." (PMID 32497022, 2020). "In addition, we measured miR-193a-5p levels in breast cancer clinical samples and found that its expression was relatively lower in tumor tissue compared with paired normal tissue and SNHG1 expression in breast cancer tissues exhibited a significant inverse correlation with miR-193a-5p expression." (PMID 32497022, 2020). "For instance, in breast cancer, E2F1 binds to the SNHG1 promoter and enhances SNHG1 transcription, which in turn promotes hTERT expression by sponging miR-18b-5p." (PMID 37612721, 2023). "This highlights that SNHG1 can suppress tumor progression and improve DDP sensitivity via the epigenetic silencing of miR-381 in breast cancer." (PMID 34806925, 2021). "Collectively, these findings demonstrated that silencing SNHG1 reduced the metastatic and DDP-resistant phenotypes of breast cancer cells via upregulating miR-381 expression." (PMID 34806925, 2021). "Totally, these findings indicated that SNHG1 downregulation improved breast cancer cell DDP sensitivity, highlighting its key regulatory roles in breast cancer chemoresistance." (PMID 34806925, 2021). "Together, these data suggest that SNHG1 acts as a sponge to inhibit miR-193a-5p and thus activates HOXA1 expression in breast cancer cells." (PMID 32497022, 2020). "Here, we show that SNHG1 is an oncogenic lncRNA that interacts with miR-193a-5p to reduce its repression of the HOXA1 gene and thus accelerate breast cancer development." (PMID 32497022, 2020). "SNHG1 knockdown or NC MDA-MB-231 cells were subcutaneously injected into different flanks of nude mice and we found that SNHG1 silencing led to reduced breast cancer cell growth." (PMID 32497022, 2020). "We also measured SNHG1 expression using Q-RT-PCR in MCF10 mammary epithelial cell lines and four breast cancer cell lines (MDA-MB-231, MDA-MB-468, MCF7, and T47D)." (PMID 32497022, 2020).
breast cancer (continued). "Nevertheless, our study first demonstrated that SNHG1 knockdown could overcome breast cancer DDP resistance, which may provide a novel therapeutic target to improve the outcome of breast cancer patients with DDP resistance." (PMID 34806925, 2021). "Small nucleolar RNA host gene 1 (SNHG1) is up-regulated in lung cancer, breast cancer and HCC." (PMID 27517149, 2016). "In this study, we show that SNHG1 contributed to tumor progression and DDP resistance in breast cancer cells by inhibiting miR-381 expression through a novel epigenetic mechanism, highlighting an attractive therapeutic target to obstruct tumor progression and overcome breast cancer DDP resistance." (PMID 34806925, 2021).